KCNK3 (potassium two pore domain channel subfamily K member 3)
Description:
K(+) channel that conducts voltage-dependent outward rectifying currents upon membrane depolarization. Voltage sensing is coupled to K(+) electrochemical gradient in an 'ion flux gating' mode where outward but not inward ion flow opens the gate. Changes ion selectivity and becomes permeable to Na(+) ions in response to extracellular acidification. Protonation of the pH sensor His-98 stabilizes C-type inactivation conformation likely converting the channel from outward K(+)-conducting, to inward Na(+)-conducting to nonconductive state. Homo- and heterodimerizes to form functional channels with distinct regulatory and gating properties. Allows K(+) currents with fast-gating kinetics important for the repolarization and hyperpolarization phases of action potentials (By similarity). In cerebellar granule cells, heteromeric KCNK3:KCNK9 channel may hyperpolarize the resting membrane potential to limit intrinsic neuronal excitability, but once the action potential threshold is reached, it may support high-frequency action potential firing and increased neuronal excitability (By similarity). Dispensable for central chemosensory respiration i.e. breathing controlled by brainstem CO2/pH, it rather conducts pH-sensitive currents and controls the firing rate of serotonergic raphe neurons involved in potentiation of the respiratory chemoreflex. Additionally, imparts chemosensitivity to type 1 cells in carotid bodies which respond to a decrease in arterial oxygen pressure or an increase in carbon dioxide pressure or pH to initiate adaptive changes in pulmonary ventilation (By similarity). In adrenal gland, contributes to the maintenance of a hyperpolarized resting membrane potential of aldosterone-producing cells at zona glomerulosa and limits aldosterone release as part of a regulatory mechanism that controls arterial blood pressure and electrolyte homeostasis (By similarity). In brown adipocytes, mediates K(+) efflux that counteracts norepinephrine-induced membrane depolarization, limits Ca(2+) efflux and downstream cAMP and PKA signaling, ultimately attenuating lipid oxidation and adaptive thermogenesis (By similarity).
Synonyms: TASK; TASK1; K2p3.1; TASK-1; DDSA; OAT1; PPH4; TBAK1
Tractability: Small molecule: an approved drug acts on it; a structure with a bound ligand is known; a high-quality ligand is known; it belongs to a druggable protein family. Antibody: UniProt places it where antibodies can reach, with high confidence; its Gene Ontology location is reachable by antibodies, with high confidence; UniProt predicts a signal peptide or a membrane-spanning region. PROTAC: a small molecule that binds it is known.
Target class: Two-pore domain potassium channel; Voltage-gated ion channel; Ion channel; Potassium channels
Chemical probes: ML365 (high quality), ML365 Analog
Gene: Protein-coding gene on chromosome 2 (26,692,722 to 26,733,420, forward strand). Ensembl gene ENSG00000171303.
Subcellular location: Cell membrane
Pathways (Reactome):
Muscle contraction: Phase 4 - resting membrane potential
Neuronal System: TWIK-releated acid-sensitive K+ channel (TASK)
Gene Ontology:
Molecular function: monoatomic ion channel activity; outward rectifier potassium channel activity; potassium ion leak channel activity; protein binding; protein heterodimerization activity; S100 protein binding; sodium channel activity; potassium channel activity; open rectifier potassium channel activity
Biological process: cellular response to acidic pH; monoatomic ion transmembrane transport; chemical synaptic transmission; detection of hypoxic conditions in blood by carotid body chemoreceptor signaling; potassium ion transport; cellular response to hypoxia; cellular response to zinc ion; cochlea development; negative regulation of cytosolic calcium ion concentration; potassium ion transmembrane transport; regulation of action potential firing rate; regulation of resting membrane potential; response to xenobiotic stimulus; sodium ion transmembrane transport
Cellular component: plasma membrane; membrane; synapse
Genetic constraint (gnomAD): Loss-of-function variants: 9 observed, 19.01 expected, observed/expected ratio (o/e) 0.47, 90% interval 0.28 to 0.83. The upper end of that interval is the gene's LOEUF score, 0.83, which puts it in group 3 of 6, group 1 being the genes least tolerant of losing a copy. Missense variants: 391 observed, 496.21 expected, observed/expected ratio (o/e) 0.79, 90% interval 0.73 to 0.86. Synonymous variants: 278 observed, 239.12 expected, observed/expected ratio (o/e) 1.16, 90% interval 1.05 to 1.28.
Gene-disease validity (ClinGen):
ClinGen rates the evidence that KCNK3 causes each of these diseases.
pulmonary arterial hypertension (autosomal dominant): Definitive. Pulmonary arterial hypertension (PAH) is a group of diseases characterized by mean pulmonary artery pressure >20 mmHg and elevated pulmonary arterial resistance leading to right heart failure.
Homologues: Orthologues: chimpanzee KCNK3 (99% identical), macaque KCNK3 (99% identical), dog KCNK3 (98% identical), pig KCNK3 (97% identical), rat Kcnk3 (92% identical), mouse Kcnk3 (91% identical), tropical clawed frog kcnk3 (83% identical), rabbit KCNK3 (75% identical), zebrafish kcnk3a (72% identical), zebrafish kcnk3b (66% identical), guinea pig KCNK3 (65% identical), Drosophila melanogaster Task6 (42% identical), and 11 more. Paralogues in human: KCNK9 (55% identical), KCNK15 (45% identical), KCNK16 (22% identical), KCNK4 (22% identical), KCNK5 (22% identical), KCNK10 (22% identical), KCNK13 (22% identical), KCNK12 (21% identical), KCNK2 (21% identical), KCNK6 (20% identical), KCNK17 (20% identical), KCNK1 (20% identical), and 2 more.
Diseases named in the same sentence as KCNK3 in open-access papers:
KCNK3 is named in the same sentence as 113 diseases in open-access papers, as found by Europe PMC text mining. Sharing a sentence is not in itself a finding about the gene and the disease. The quoted sentences say what the papers report.
pulmonary arterial hypertension (32 papers, 2015 to 2026). "BACKGROUND: Pathogenic variants in KCNK3 have been implicated in pulmonary arterial hypertension (PAH); however, the molecular mechanisms underlying this association remain insufficiently defined." (PMID 41998797, 2026). "Further, we showed that a variant in KCNK3 (potassium two-pore domain channel subfamily k member 3), associated with pulmonary arterial hypertension, was also significantly associated with AP." (PMID 36747740, 2023). "Loss of function KCNK3 mutation is one of the gene variants driving hereditary pulmonary arterial hypertension (PAH)." (PMID 34065088, 2021). "In 2013, a genetics consortium identified a collection of KCNK3 loss of function mutations as likely causative in a heritable pulmonary arterial hypertension (PAH) family and several idiopathic PAH patients." (PMID 34065088, 2021). "For example, loss-of-function mutations in the first or second pore domains of KCNK3 (respectively, p.Gly97Arg and p.Gly203Asp) cause pulmonary hypertension." (PMID 34032641, 2021). "The KCNK3 gene encodes a member of the potassium channel superfamily, which has been associated with pulmonary hypertension in humans." (PMID 26607727, 2015). "Deleterious variants within KCNK3 have been linked to pulmonary arterial hypertension." (PMID 37754822, 2023). "Several studies have shown that KCNK3 is closely associated with pulmonary arterial hypertension." (PMID 36845374, 2023). "These gene expression differences in iPS-derived mesenchymal cells suggested that KCNK3 mutation may predispose to pulmonary hypertension through mechanisms previously associated with PAH, including vascular tone, metabolism, or inflammation." (PMID 34065088, 2021). "Additionally, it needs to be noted that in Kcnk3-mutated rats, a novel model for occurrence of pulmonary hypertension was recently characterized." (PMID 31795416, 2019). "Potassium Channel Subfamily K Member 3 (KCNK3) was identified in 2013 as a predisposing gene for pulmonary arterial hypertension (PAH)." (PMID 33036472, 2020). "Canonical pulmonary arterial hypertension genes such as BMPR2, KCNK3, and TBX4 are well described, but novel associations continue to emerge." (PMID 41133550, 2025). "The KCNK3 and ADAMTS9 genes have been implicated in cardiac function, with KCNK3 identified as a predisposing factor for pulmonary arterial hypertension (PAH), primarily affecting atrial function and playing roles in rhythm regulation and cardiac conduction." (PMID 39596121, 2024). "According to the pulmonary hypertension gene curation expert panel of pulmonary hypertension of ClinGen, the association of BMPR2, KCNK3, KDR, SMAD9, and TBX4 and PH is definitive, GDF2 is strong, and AQP1 has a limited disease relationship." (PMID 35627312, 2022). "In the Human Lung Cell Atlas project, lung pericytes are identified using COX4I2, TBX5, and KCNK3 and its potential implication in pulmonary hypertension is proposed." (PMID 35722109, 2022). "It was reported that KCNK3 expression and function are incomplete in patients with idiopathic hereditary pulmonary arterial hypertension and in the PAH rat model induced by monocrotaline." (PMID 32566097, 2020). "In this study, we analyzed 7 PAH-causing genes including BMPR2, ACVRL1, ENG, SMAD9, CAV1, KCNK3, and CBLN2 in 49 CTEPH patients and 17 patients recovered from pulmonary embolism (PE) but without pulmonary hypertension(PH)." (PMID 26820968, 2016). "Potassium channel subfamily K member 3 (KCNK3, also known as TASK-1) belongs to a member of potassium channel proteins, and the suppression of KCNK3 acts as a leading player in the pathogenesis of pulmonary arterial hypertension pathogenesis with increased proliferation and inflammation." (PMID 34591125, 2021).
atrial fibrillation (16 papers, 2017 to 2025). A disorder characterized by an electrocardiographic finding of a supraventricular arrhythmia characterized by the replacement of consistent P waves by rapid oscillations or fibrillatory waves that vary in size, shape and timing and are accompanied by an irregular ventricular response. "Importantly, patients who develop PH with atrial fibrillation have a higher mortality than PH patients without atrial fibrillation, suggesting that KCNK3-LOF mutations or KCNK3-dyfunction could also contribute to the clinical deterioration of PH favoring the occurrence of atrial fibrillation." (PMID 32882918, 2020).
Hypertension (16 papers, 2013 to 2025). The presence of chronic increased pressure in the systemic arterial system. "In previous GWAS studies on blood pressure regulation, the association of ENPEP and KCNK3 with hypertension has been established, and the association between USP38 and blood pressure regulation still needs further validation." (PMID 36845374, 2023). "Overall, our findings that the common KCNK3 variant is associated with hypertension in Hispanics suggest that further work is needed to explore hypertension related salt-sensitivity in this population." (PMID 27736895, 2016). "Each copy of the KCNK3 rs2586886-G allele was associated with 13% increased odds of hypertension in Hispanics." (PMID 27736895, 2016). "Whether there is an association between KCNK3 in the regulation of obesity and hypertension remains to be further investigated." (PMID 36845374, 2023). "We used the eQTL information of all the tissues and finally identified three key genes associated with essential hypertension: ENPEP, USP38, and KCNK3." (PMID 36845374, 2023). "This gene-based association approach with tissue specificity has a lower multiple-testing burden and has identified three key genes in essential hypertension: potassium two-pore domain channel subfamily K member 3 (KCNK3), glutamyl aminopeptidase (ENPEP), and ubiquitin-specific peptidase 38 (USP38)." (PMID 38786976, 2024). "Furthermore, statistical analyses indicated that KCNK3 (TASK-1) variants are associated with hyperaldosteronism and hypertension." (PMID 36500386, 2022). "Female TASK1-/- mice lacking KCNK3 develop hypokalemia and low-renin hypertension that is normalized by mineralocorticoid receptor blockade but controlled by ACTH, a consequence of misallocation of aldosterone synthase in the zona fasciculate." (PMID 27736895, 2016).
pulmonary hypertension (15 papers, 2015 to 2022). Increased pressure within the pulmonary circulation due to lung or heart disorder. "It has been shown that pharmacological activation of KCNK3 with ONO-RS-082 in vivo can alleviate the symptoms of pulmonary hypertension (PH) caused by monocrotaline in rats." (PMID 36500386, 2022).
channelopathy (9 papers, 2017 to 2025). Channelopathies are a group of diseases caused by the dysfunction of ion channel subunits or their interacting proteins. "The remaining one patient harbored a missense variant in KCNK3, which was the first replicative finding of channelopathy in Japanese population." (PMID 28388887, 2017). "In the remaining one family, the patient carried a pathogenic variant in a member of potassium channels, KCNK3, which was the first replicative finding of channelopathy in an Asian population." (PMID 28388887, 2017). "KCNK3 loss of function mutations are responsible for the first channelopathy identified in PAH." (PMID 33036472, 2020). "Heterozygous de novo gain-of-function mutations in KCNK3, which encodes the two-pore-domain K+ channel TASK-1, cause a channelopathy characterized by developmental delay with sleep apnea." (PMID 36195757, 2022). "Roles of genetic variants in three channelopathy genes—ABCC8, ATP13A3, and KCNK3—have been validated in multiple independent studies, and explain ~2.7% of PAH cases." (PMID 35204766, 2022). "While as of yet, KCNK3 and ABCC8 mutations are the only channelopathies known to cause PAH, there is growing data supporting the significant role that potassium channels play in the cellular mechanisms underlying abnormal PAEC and PASMC behavior." (PMID 36291551, 2022).
hyperaldosteronism (9 papers, 2015 to 2023). Overproduction of aldosterone by the adrenal glands, which may lead to hypokalemia and/or hypernatremia. "Global Kcnk3 knockout mice display a phenotype of mild hyperaldosteronism and single nucleotide polymorphisms in the KCNK3 gene were associated with plasma aldosterone levels." (PMID 34831137, 2021). "For example, only female KCNK3-/- mice exhibited hyperaldosteronism, and testosterone-treated KCNK3-/- females showed normal aldosterone levels, implying an androgen-protective effect in male mice." (PMID 26807823, 2016). "Additionally, this study showed in a rodent model, that genetic disruption of KCNK3 produces hyperaldosteronism." (PMID 38162683, 2023). "Kcnk3 (TASK-1) knockout mice show the expression of Cyp11b2 in the reticulo-fasciculata zone instead of in the ZG and develop severe hyperaldosteronism (including hypokalemia and low renin levels) remediable by glucocorticoids, representing clinical features of FH-I90." (PMID 31695023, 2019).
lung carcinoma (7 papers, 2013 to 2023). "TWIK-related acid-sensitive potassium channel 1 (TASK1), encoded by KCNK3, is associated with pulmonary circulation and controls pulmonary arterial tone, which may contribute to poor prognosis in lung cancer patients." (PMID 35676660, 2022). "However, KCNK3 has been reported to regulate apoptosis and proliferation in lung cancer, and KCNK3 knockdown enhances apoptosis of tumor cell lines." (PMID 30305115, 2018). "The role of the two-pore domain K+ (K2P) channel TASK-1 (KCNK3) in lung cancer is at present unknown." (PMID 27294516, 2016). "Our findings implicated that KCNK3 could be served as a key molecular regulator of cell metabolism and aberrant cell proliferation of LUAD, which provides a further understanding of the underlying pathogenesis of lung cancer." (PMID 35963847, 2022). "However, its additional biological role and profound mechanism of KCNK3 in early-stage lung cancer, especially adenocarcinoma, are still unknown." (PMID 35963847, 2022). "Compared with normal tissues, the expression of ADM2, CLIC6, KIF20A, LAD1, MUC5B, and TNS4 was up-regulated, and the expression of ATG16L2, KCNK3, MAFF, NKD1, and SPATA13 was down-regulated in lung cancer tissues." (PMID 34804921, 2021).
breast carcinoma (6 papers, 2013 to 2024). "KCNK3 (potassium channel, subfamily K, member) was induced by 1,25(OH)2D3 in artery smooth muscle cells, and EFTUD1 (elongation factor Tu GTP binding domain containing 1) in oral squamous carcinoma, breast cancer associated fibroblasts, immortalized prostate cells and lymphoblastoid cell lines." (PMID 23497279, 2013). "A low level of KCNK3 has been found in MCF-7 and MDA-MB-231 breast cancer cells, but the role of KCNK3 in breast cancer remains unknown at the present time." (PMID 30305115, 2018).
lung adenocarcinoma (5 papers, 2016 to 2024). A carcinoma that arises from the lung and is characterized by the presence of malignant glandular epithelial cells. "For instance, TWIK‐related acid‐sensitive potassium channel 1 (TASK‐1 or KCNK3) has been identified as a potential therapeutic target in lung adenocarcinoma, as it inhibits proliferation and glucose metabolism through the activation of the AMPK–TXNIP pathway." (PMID 39534557, 2024). "Potassium channel subfamily K Member 3 (KCNK3), a genetic member of the two-pore domain potassium (K2P) channels, is still unknown in lung adenocarcinoma." (PMID 36366411, 2022). "However, TWIK-related acid-sensitive potassium channel 1 (TASK-1, also called KCNK3), a genetic member of K2P channels, remains an enigma in lung adenocarcinoma (LUAD)." (PMID 35963847, 2022).
Stroke (5 papers, 2013 to 2023). Sudden impairment of blood flow to a part of the brain due to occlusion or rupture of an artery to the brain. "We found clear evidence for stroke risk for four loci (SH2B3, FGF5, PITX2, and KCNK3)." (PMID 37479695, 2023).
Sleep apnea (4 papers, 2021 to 2025). An intermittent cessation of airflow at the mouth and nose during sleep is known as sleep apnea. "Although other developmental disorders have been linked with sleep disturbances, the universality of sleep apnea in 100% of probands with pathogenic KCNK3 mutations is unusual." (PMID 36195757, 2022). "In this study, we describe nine probands with de novo missense mutations in KCNK3 who exhibit global developmental delay, hypotonia, a range of structural malformations and sleep apnea." (PMID 36195757, 2022). "Moreover, no causal gene (except KCNK3) has sleep apnea recorded in every DDD proband with a diagnostic variant; the universality of sleep apnea in 100% of probands with pathogenic KCNK3 mutations is therefore highly unusual." (PMID 36195757, 2022). "KCNK3 encodes TASK-1, a K+ channel implicated in the control of breathing, but its link with sleep apnea remains poorly understood." (PMID 36195757, 2022). "Furthermore, no causal gene (except for KCNK3) has sleep apnea recorded in every DDD proband with a diagnostic variant." (PMID 36195757, 2022).
colorectal cancer (3 papers, 2020 to 2026). A primary or metastatic malignant neoplasm that affects the colon or rectum. "Also, KCNK3 was correlated with prolonged survival after surgery in colorectal cancer." (PMID 35372462, 2022).